TTC27 (tetratricopeptide repeat domain 27)
Synonyms: FLJ20272; EMW1; TRD1
Tractability: PROTAC: ubiquitination databases record sites on it; its protein half-life has been measured.
Gene: Protein-coding gene on chromosome 2 (32,628,032 to 32,821,051, forward strand). Ensembl gene ENSG00000018699.
Subcellular location (Human Protein Atlas): Mitochondria; Nucleoli
Gene Ontology:
Molecular function: protein binding
Genetic constraint (gnomAD): Loss-of-function variants: 60 observed, 96.23 expected, observed/expected ratio (o/e) 0.62, 90% interval 0.51 to 0.77. The upper end of that interval is the gene's LOEUF score, 0.77, which puts it in group 3 of 6, group 1 being the genes least tolerant of losing a copy. Missense variants: 965 observed, 925.66 expected, observed/expected ratio (o/e) 1.04, 90% interval 0.99 to 1.1. Synonymous variants: 361 observed, 337.54 expected, observed/expected ratio (o/e) 1.07, 90% interval 0.98 to 1.17.
Homologues: Orthologues: chimpanzee TTC27 (99% identical), macaque TTC27 (98% identical), pig TTC27 (90% identical), dog TTC27 (90% identical), rabbit TTC27 (89% identical), guinea pig TTC27 (89% identical), mouse Ttc27 (85% identical), tropical clawed frog ttc27 (66% identical), zebrafish ttc27 (59% identical), Caenorhabditis elegans trd-1 (29% identical), Drosophila melanogaster CG5290 (29% identical).
Diseases named in the same sentence as TTC27 in open-access papers:
TTC27 is named in the same sentence as 4 diseases in open-access papers, as found by Europe PMC text mining. Sharing a sentence is not in itself a finding about the gene and the disease. The quoted sentences say what the papers report.
colorectal cancer (1 paper, 2021). A primary or metastatic malignant neoplasm that affects the colon or rectum. "The subnetworks revealed genes that are previously reported as CRC-associated as well as several yet undeciphered genes that may contribute colorectal cancer, such as DNAAF5, RASL10B, DUSP19, and TTC27." (PMID 34790220, 2021).
cancer (2 papers, 2024 to 2025). A tumor composed of atypical neoplastic, often pleomorphic cells that invade other tissues. "Although TTC27 is absent in three cancer gene databases, the breakpoints disrupt MSigDB and COSMIC CGC genes BIRC6 and LTBP1, resulting in a LTBP1-BIRC6 gene fusion of unclear effect." (PMID 38947031, 2024).
TTC27 also shares sentences with these, for which no sentence is quoted: schizophrenia (1 paper); tumor (1).